IGF1 (insulin like growth factor 1)
Diseases named in the same sentence as IGF1 in open-access papers (continued):
Sharing a sentence is not in itself a finding about the gene and the disease.
cancer (continued). "CAF from low-grade but not high-grade carcinomas required insulin-like growth factor 1 and transforming growth factor beta 1 to stimulate carcinoma growth." (PMID 23056402, 2012). "Given that mTOR activation isregulated mainly by the IGF-1/AKT pathway, attenuation of AKT activity as observed in ourexperimental cancer cachexia model should further facilitate protein translation inhibitiondue to mTOR inactivation and the consequent hypophosphorylation of EIF4Ebp1." (PMID 21069263, 2011). "As IGF-1 and EGF are both known to stimulate survivin in cancer cells, we next tested whether these growth factors can also induce survivin in pancreatic β-cells." (PMID 20807437, 2010). "After adjustment for other factors, preoperative serum total IGF-1 or IGFBP-3 levels failed to predict cancer death and recurrence." (PMID 18781172, 2008). "IGF-1 has been shown to act as a potent mitogen, with anti-apoptotic actions, on various cancer cells, whereas IGFBP-3 may have IGF-1-independent pro-apoptotic activity." (PMID 19570255, 2002). "Therefore, targeting TM4SF4 may reduce ICL expression by decreasing extracellular IGF1 and OPN levels, thereby improving the efficiency of cancer therapies." (PMID 41356204, 2026). "In addition, IGF-1 signaling is crucial for sustaining cancer cell viability by stimulating mitochondrial biogenesis and mitophagy through the induction of BNIP3, thereby influencing therapy responses and cancer phenotype evolution." (PMID 41583513, 2026). "While the role of IGF1 isoforms in hypoxic conditions remains unexplored, future research could investigate their potential contributions to tumour progression and therapeutic resistance in the TME, offering new insights into cancer biology." (PMID 39796756, 2025). "Moreover, markers of cellular stress, such as IGF-1, were reduced in the FMD group, suggesting that the diet may create a less favorable environment for cancer cell proliferation." (PMID 40296920, 2025). "Previous studies by our group and others have shown that treatment with MIA-602 and MIA-690 suppresses tumoral IGF1 expression in mouse models of human cancers without significantly altering serum GH levels, further supporting the GH-independent actions of these peptides." (PMID 40244089, 2025). "Therefore, it can be speculated that the expression of VEGF-A induced by IGF-1 in RPE cells may be mediated by the transcriptional activity of PKM2, as occurs in cancer cells." (PMID 39769402, 2024). "Therefore, the action of IGF-1 might be minimally affected by IGFBP but rather influenced by the activation of IGF-1R and its downstream signaling pathways to impact cancer progression." (PMID 39290325, 2024). "On the contrary, other evidence demonstrates that cancer treatment might negatively affect CAFs by enhancing their secretion of IGF1/IGF2, with a negative impact on cancer progression." (PMID 38892104, 2024). "Moreover, several growth factors, including insulin-like growth factor 1 (IGF-1), basic fibroblast growth factor 2 (FGF2), and epidermal growth factor (EGF), can greatly activate the PI3K-AKT pathway, thereby facilitating malignant behaviors of cancers 12-16." (PMID 37496999, 2023). "This suggests that, although many cancer cells rely on glucose metabolism, glucose is not the only key driver of cancer growth and progression in metabolic disorders, in which other factors such as IGF-1 may be involved." (PMID 37106164, 2023). "However, this rescue of STAT3 phosphorylation by insulin, IGF1 and leptin was no longer detectable when the cancer cells were treated with the cholesterol-depleting agent MβCD." (PMID 37907500, 2023). "They activate cancer cell signaling pathways and transcription factors, including IGF1/α6β4 complex, FGFR2, TIMP, DNA replication and mTOR signaling, Smad7, KLF4, and TBX2, and downstream proto-oncogenes such as MYC, MET, and CDK1, which facilitate cancer progression." (PMID 37046676, 2023).
cancer (continued). "In addition, Insulin-like growth factor-1/2(IGF1/2), chemokine (C-X-C motif) ligand 12(CXCL12), and beta-hydroxybutyrate produced by CAFs can induce autophagy of cancer cells after RT, and promote recovery of irradiated cancer cells and tumor regeneration after RT." (PMID 37600785, 2023). "Moreover, serine and 1-carbon metabolism link mTOR signals to DNA methylation, resulting in oncogene mutations that provide continuous activation of growth factor [insulin-like growth factor (IGF)-1, epidermal growth factor (EGF), and EGF receptor] signals for cancer cells." (PMID 37187454, 2023). "Notably, people or rodents with developmental GH/IGF-1 show rare-to-no cancer occurrence due to the overexpression of DNA repair genes and perpetual strengthening of DNA repair capacity." (PMID 35855334, 2022). "The biological effects of IGF-1 are mediated by IGF-1R, a transmembrane protein that possesses a tyrosine kinase domain that, once activated, initiates a cascade of events involving AKT, RAF-1/MEK/ERK proteins, the major signaling pathway involved in cancer proliferation and survival." (PMID 35162142, 2022). "Downstream in the GH/IGF1 signaling there is an strong analogy between inhibiting the GHR in mice with BM001 and the inhibitory effect of the small molecule S3I-201 on STAT3 with the same cancer cells: Both inhibitors resulted in tumor regression of MM231 xenografted mice." (PMID 35966052, 2022). "The IGF1 is a polypeptide that is mediated mitogenic and anti-apoptotic effects via IGF1 receptor that is a type 2 tyrosine kinase receptor, and the accumulating evidence indicated that IGF axis played pivotal roles in human cancer progression and can be targets for therapeutic intervention." (PMID 35317079, 2022). "In recent cancer therapy advances, tumor angiogenesis became a target, whereby a range of angiogenic factors, such as vascular endothelial growth factor (VEGF), insulin-like growth factor-1 (IGF-1), platelet-derived growth factor (PDGF), and epidermal growth factor (EGF), are inhibited." (PMID 36555410, 2022). "As oncogenic Notch1 and over-activation of IGF1 are known to promote cancer development, LUNAR1 may be active in other cancers with Notch1 alterations." (PMID 36230680, 2022). "To examine the effect of short-term disruption of IGF-1 signalling on increased energy balance-related changes in lipid storage and AT function, we employed a pharmacological approach using the IGF-1 R-specific antibody cixutumumab, which has been used in humans to treat a range of malignancies." (PMID 35734881, 2022). "The perturbational class identified in our study, namely PI3K inhibitors, mTOR inhibitors, IGF-1 inhibitors, JAK inhibitors, DNA dependent protein kinase inhibitors, HDAC inhibitors, and FLT3 inhibitors, were also reported to mediate immune modulation in various cancers." (PMID 35954379, 2022). "Since the IGF axis could contribute to cancer progression and invasion, it is now widely accepted that aberrant methylation of IGFBP7, IGFBP-4, IGFBP-3, IGF-1R, IGF-1, and IGF-II promoters could be a potential factor in various common human cancers." (PMID 33768092, 2021). "Both HGF and IGF1 activated signaling pathways lead to BC cell proliferation, migration and invasion, and are critically involved in the induction/maintenance of EMT and cell stemness, which are fundamental in metastatic spread and resistance to anti-cancer treatments." (PMID 34195201, 2021). "However, based on studies involving heterogeneous human cancers (including CRC), the mechanisms of this correlation, could only be partially explained by changes in the insulin/IGF-1 axis." (PMID 34208601, 2021). "However, the correlations of IGF-1 and IGF-1R to prognosis and tumor-infiltrating lymphocytes in different cancers remain unclear." (PMID 34804946, 2021).
cancer (continued). "This research comprehensively analyzed the expression pattern of IGF-1 and IGF-1R and the influence of IGF-1 and IGF-1R on clinical significance in prognosis prediction among 33 types of malignancies using The Cancer Genome Atlas (TCGA) and the Cancer Cell Line Encyclopedia (CCLE) databases." (PMID 34804946, 2021). "IGF-1 and its receptor IGF-1R are involved in these critical pathways and therefore play a pivotal role in healthy tissue homeostasis but also a far less desirable role in diseases such as cancer where they can be responsible for the survival and proliferation of malignant cells." (PMID 33557137, 2021). "Consequently, a wide spectrum of cellular receptors and proteins, including transferrin receptor, insulin-like growth factor 1 (IGF-1) receptor, folate receptor or integrins has been widely investigated to date as factors for increasing drug selectivity against cancer cells." (PMID 34771587, 2021). "Moreover, IGF1 and IGF2 mediate cancer cells’ resistance to paclitaxel in murine models, suggesting that lowered IGF bioavailability could heighten chemotherapy." (PMID 34073987, 2021). "Cancer cells could dominate the IRS expression level to promote proliferation and survival, along with a response from IGF-1 and its downstream signal transducers, resulting in an elevated expression level of ERα in hormone-dependent BC, which converts to TNBC through the tumor progression sequence." (PMID 34069906, 2021). "Interestingly, positively correlated loci represented cancer driver genes (MYC, PRKCD, RB1, CDK6), molecules involved in immune response (MALT1, PIK3CG), as well as cellular and hormonal signaling (HGF, PTPN13, IGF1, SMAD1, ESR1, CTGF)." (PMID 34368147, 2021). "Additionally, this combination has been shown to have synergistic effects in non-cancer clinical populations on outcomes relevant to cancer including body composition, aerobic fitness, fasting insulin and glucose, and IGF-1." (PMID 34629067, 2021). "Insulin, insulin-like growth factor-1 (IGF-1), and insulin-like growth factor-2 (IGF-2) are ligands for the transmembrane tyrosine kinase receptors, insulin receptor (IR), and IGF-1 receptor (IGF-1R), which have important roles in growth, development, cancer, and metabolic disease." (PMID 33604295, 2020). "IGF-1 has been reported to upregulate angiogenesis and tumor invasion by activating matrix metalloproteinases, which are well known nonglycolytic proteolytic enzyme biomarkers in several cancer types." (PMID 32722232, 2020). "However, it is still not clear how BNIP3 expression, its induction by IGF-1, or the role of mitophagy in cancer cell metabolism is regulated or integrated with mitochondrial biogenesis and mitochondrial function." (PMID 31936236, 2020). "The studies described in this review article were designed to evaluate the hypothesis that life-long lack of exposure to IGF1 in LS activates cancer-protecting pathways, including apoptosis and autophagy." (PMID 31208077, 2019). "Therefore, we provide physiological confirmation of the hypothesis that IGFs signaling in RCC is mediated mainly by circulating ligand proteins (IGF1 and IGF2) from sources other than RCC cancer tumor itself, as suggested before." (PMID 30929166, 2019). "Notably, resistance to the growth limiting effects of STF has been observed in cancer cells carrying mutations that cause a constitutive activation of the PI3K pathway, since these cells proliferate even in the absence of insulin or IGF-1." (PMID 31113478, 2019). "Taken together, the production of IGF-1 and the activation of expression of CCR7 result in lymphangiogenesis and may promote cell migration toward lymph node in middle stage LSCC, suggesting that cancer cells may metastasize through lymph node in LSCC." (PMID 31217907, 2019).
cancer (continued). "IGF1 promotes the development and cytotoxic activity of human NK cells, therefore the reduction of this protein by the augmented expression of IGF2 by miR-483-5p, or by the direct targeting of IGF1 by miR-483-3p, provide a protection to cancer cells by suppressing NK cells activity." (PMID 29867024, 2018). "Doing a differential expression between the two clusters of cancer fibroblasts, we found metastatic fibroblasts were found to express higher levels of soluble factors compared to primary fibroblasts including, CXCL12, S100A6, S100A10, SFRP2,SFRP4,IGF1, CXCL14, ANGPTL4 and IL6." (PMID 30383866, 2018). "Therefore, in parallel to IGF-1, TGF-β could contribute to the RhoA-dependent enhancement of cancer cell invasiveness via PAI-1." (PMID 29535813, 2018). "We cannot also rule out the possibility that cancer cells may induce expression of IGF1 from stromal cells by stimulating tumor microenvironment as tumors in MP subtype have higher fraction of non-tumor cells." (PMID 29725014, 2018). "It has been proposed that metformin exerts its anti-cancer properties through direct effects on cancer cells, particularly through inhibition of the AMPK/mTOR pathway, and indirect effects by decreasing glucose, insulin, insulin-like growth factor 1 (IGF-1) levels, and other inflammatory factors." (PMID 29113364, 2017). "Thus, IGF-1 and IGFBP-1 may play important roles in modulating the effect of exercise serum on cancer cell growth and survival." (PMID 28481292, 2017). "Moreover, AG1024 treatment did not modify CCL5 expression in MDA-MB231 cells thus indicating that IGF-1 did not control CCL5 in cancer cells." (PMID 27027351, 2016). "From the point of view of cancer or tumor research, it was reported that miR-103 is part of the G1/S transition regulatory network, by targeting CCNE1, CDK2, and CREB1 (cAMP responsive element binding protein 1) during IGF-1 simulated proliferation in mouse crypt cells." (PMID 26935418, 2016). "Inhibiting the IGF-1 signaling pathway in cancer therapy may have no adverse effects, since IGF-1 concentrations are reduced following birth." (PMID 25289088, 2014). "Moreover, XMetS did not influence the effects of IGF-1 on the proliferation of both cancer cell lines (data not shown)." (PMID 24533136, 2014). "Thus, GSK3i alone specifically stimulates Kitl expression offering a pharmacological approach to increase Kitl/KITLG levels in gastrointestinal muscles without reproducing IGF1’s actions promoting cellular stress, aging and cancer." (PMID 24116170, 2013). "Similarly to KIT, PDGFRA and their ligands, insulin-like growth factor (IGF)-1 receptor (IGF1R), a type 2 RTK, and its ligands IGF1 and IGF2 play critical roles in normal growth and development, as well as in cellular stress, aging and cancer by stimulating protein synthesis and the cell cycle." (PMID 24116170, 2013). "More interestingly, we showed that activation of PI3K signaling by IGF-1 abrogated Aur-A inhibitory VX-680 induced apoptosis, whereas combination of VX-680 and PI3K inhibitor induced synergistic effects on inducing apoptosis and reducing migration in cancer cells." (PMID 19891769, 2009). "This demonstrates that IGF-1 levels in the blood serum may not be the optimal marker for cancer progression in this model, but simply reflects IGF-1 production from the liver." (PMID 19171036, 2009).
cancer (continued). "Similar to how natural compounds like Rebeccamycin are thought to exert anti-cancer effects by modulating the PI3K/AKT signaling pathway, JadeAging may potentially achieve its anti-aging and antioxidant effects through the modulation of the insulin/IGF-1 and TOR pathways." (PMID 41601965, 2026). "Evidence indicates that the growth hormone (GH)-IGF-1 axis plays a significant role in cancer incidence and progression, supported by epidemiological studies linking elevated plasma IGF-1 levels to increased cancer risk and the observed absence of cancers in individuals with GH/IGF-1 deficiency." (PMID 39940361, 2025). "Furthermore, we aimed to extend our previous investigation and compare levels of IGF-1, IGF-2, PAPP-A, PAPP-A2, STC1, and STC2 in corresponding ascites and serum samples, providing new insights into the mechanisms behind IGF-mediated tumorigenicity and cancer biology." (PMID 38396692, 2024). "In addition to FGFR1 and FGFR3, studies have shown that insulin-like growth factor 1 (IGF-1) and the lipid hydroperoxidase, GPX4, could activate the PI3K/AKT and ERK pathways to induce the EMT program, and IGF-1R phosphorylation in cancer cells led to the production of DTPs." (PMID 36313710, 2022). "Therefore, the distinct prognostic value of changeable IGF-1/IGF-1R expression across different cancers may result from its synthetic effect of immune suppressive activity and tumor suppressive activity in each cancer type." (PMID 34804946, 2021). "In addition, due to the similar structure of insulin and IGF-1, IGF-1 can indirectly act on the heterozygous receptor to play its biological function, promote the corresponding signal transduction and cell proliferation, thus increasing the possibility of malignant tumor." (PMID 33468224, 2021). "Thus, homeostatic interactions between GH and IGF-1 and subsequent net effects in cancer is unexplored despite being very provocative towards explaining oncogenic processes like EMT, drug efflux, apoptosis, cancer stemness, and metastases where GH and IGF-1 overlap." (PMID 33291663, 2020). "Thus, IGF-1R levels alone will not necessarily determine cancer cell responses to IGF-1 and anti-IGF-1R therapies, as IGF-1R activity and downstream signaling are influenced by adhesion signals and activation of other signaling pathways, which are discussed further below." (PMID 26191041, 2015). "Since IGF-1 is a growth factor essential for maintaining systemic homeostasis in key tissues such as the muscles and heart, targeting of IGF-1 may not be feasible for attenuating cancer risk and/or progression." (PMID 25062088, 2014). "Taken together, this study reveals a novel mechanism by which IGF-1 activates MDM2 via the mTOR pathway, and that pharmacologic inhibition of mTOR combined with chemotherapy may be more effective in treatment of a subset of cancers harboring increased MDM2 activation." (PMID 23638184, 2013). "The potential translational significance of these findings is that GSK3i may allow the stimulation of KITLG expression e.g. in patients with ICC loss without concomitant activation of the pathways that mediate IGF1’s actions promoting cellular stress, aging and cancer." (PMID 24116170, 2013). "Thus, low IGF-1 serum levels attenuated IGF-1/mTORC1-mediated cell proliferation and increased FoxO-mediated anti-oxidative responses by upregulation of superoxide dismutase and catalase as well as by FoxO-driven pro-apoptotic responses, all of which are most important cancer-preventive mechanisms." (PMID 22891897, 2012). "In hypopharyngeal squamous cell carcinoma, the crosstalk between cancer cells and TAMs mediates tumor progression through the transcription factor DACH1, which acts as a negative transcriptional regulator of IGF1." (PMID 38892104, 2024).